INS (insulin)
Diseases named in the same sentence as INS in open-access papers (continued):
Sharing a sentence is not in itself a finding about the gene and the disease.
Hyperglycemia (continued). "Impaired insulin responses at these tissues will cause abnormal glucose metabolism and the followed hyperglycemia." (PMID 28117714, 2017). "In this study we observed that in both the NDF and FDF-fed groups, with 45 & 55 mg/kg STZ frank hyperglycaemia was developed with < 46.8% serum-insulin, a severe deficiency typical of diabetes type-1." (PMID 28129400, 2017). "The failure of pancreatic beta cells to produce insulin, and the impairment of insulin action, play a central role in the disruption of glycemic homeostasis, leading to hyperglycemia, a hallmark of DM." (PMID 27366200, 2016). "This disease is characterized by hyperglycemia and glucose intolerance and symptoms caused by failure to produce and/or respond to insulin." (PMID 27486508, 2016). "It has recently been shown that MCre mice express a human growth hormone (hGH) minigene in pancreatic islets, and that local hGH secretion is associated with increased insulin content and resistance to streptozotocin-induced hyperglycaemia." (PMID 27677764, 2016). "Although AKH peptide levels have not been measured directly, assessing the relative contribution of AKH to hyperglycemia in insulin-deficient states can be done genetically and remains an open question." (PMID 27053133, 2016). "In this condition, post meal or after a glucose load, the raised blood glucose levels cause insulin secretion but hyperglycemia occurs." (PMID 27065949, 2016). "For example, the fetal pancreas would respond to maternal hyperglycemia by increasing insulin production and subsequently cause beta cell hyperplasia in the islets of Langerhans." (PMID 27476441, 2016). "A sudden increase in blood glucose levels, causing hyperglycemia in NIDDM is due to insulin’s inability to effectively utilize the glucose produced by the hydrolysis of dietary carbohydrates by carbohydrate hydrolyzing enzymes." (PMID 27036710, 2016). "In patients with poorly controlled diabetes, initial treatment of hyperglycemia with insulin has been shown to cause transient elevation of liver enzymes." (PMID 27699071, 2016). "Stretozotocin (STZ) only-treated groups exhibited hyperglycemia, polydipsia, polyuria, weight loss, glucose intolerance, low fasting plasma insulin and reduced hepatic glycogen content compared to the control group." (PMID 27073901, 2016). "DM is characterized by hyperglycemia and alteration of carbohydrate, fat, and protein metabolisms associated with absolute or relative deficiency in insulin secretion or insulin action." (PMID 26881248, 2016). "A false hypoglycaemia would "only" risk exposing the patient to hyperglycaemia, however, a false hyperglycaemia exposes the patient to a risk of potentially severe hypoglycaemia as a result of increased insulin rate." (PMID 26801983, 2016). "This study showed that protamine zinc insulin was problematic, causing regular episodes of hyperglycemia and hypoglycemia." (PMID 27253523, 2016). "This further elevation of hyperglycemia in the rapa-treated mice was associated with diminished circulating insulin, suggesting that a hypoinsulinemic-associated hyperglycemia can develop over time with rapa-treatment." (PMID 27922820, 2016). "Another effect of hyperglycemia on bone turnover is dependent on deficiency of insulin and insulin-like growth factor-1 (IGF-1)." (PMID 27338453, 2016). "Hyperglycaemia decreased insulin secretion which is associated with the reduction in β-cell mass and impaired β-cell function." (PMID 27200371, 2016). "Persistent hyperglycemia causes increase in cellular glucose level in tissues undergoing insulin-independent glucose uptake such as eye lens, retina, kidney, and peripheral nerves, leading to secondary late stage diabetic complications." (PMID 27846886, 2016).
Hyperglycemia (continued). "The diabetic phenotype is quite severe and is characterized by development of hyperglycemia, hypoinsulinemia weight loss, and ketonuria requiring insulin therapy for survival." (PMID 27595114, 2016). "We found that the risk of death due to fatal hyperglycaemia was increased among individuals treated with insulin (OR 4.40, 95% CI, 1.96, 9.85)." (PMID 27768720, 2016). "T1D is characterized by the destruction of pancreatic beta cells and insulin-deficient hyperglycemia." (PMID 27520566, 2016). "Management of hyperglycemia by chemical drugs or insulin causes numerous problems such as fatty liver induced by insulin." (PMID 27054124, 2016). "Type 1 DM (T1DM) is characterized by hyperglycaemia because of a deficiency in insulin that is the result of autoimmune destruction of β‐cells in the pancreas." (PMID 26914991, 2016). "The destruction of beta cells of pancreas causes hyperglycemia, which can be treated by insulin therapy to control hyperglycemia, but it leads to increase in weight gain as well as ovarian hyperandrogenism." (PMID 27274883, 2016). "While in the STZ induced diabetic mice, where insulin signal is deficient, Inpp5f is mainly regulated hyperglycemia and hyperlipidemia." (PMID 26908121, 2016). "Ingestion of carbohydrate-rich foods is absorbed into the small intestine, which in turn cause increased glucose absorption, hyperglycemia, rapid release of insulin, and overall results in hypoglycemia." (PMID 27065949, 2016). "Oxidative stress and hyperglycemia in metabolic diseases lead to adverse neurophysiological phenomena, including neuronal loss, synaptic dysfunction, and improper insulin signaling, resulting in Parkinson’s disease (PD)." (PMID 27065205, 2016). "The association of hyperglycemia and hyperlipidemia with enhanced lifespan seems counterintuitive in that increased insulin sensitivity is most often associated with longer lifespan." (PMID 27590905, 2016). "BTBR mice are naturally insulin-resistant, and when the ob/ob mutation is placed on this strain, the mice exhibit sustained hyperglycemia from an early age, in contrast to ob/ob mice on the C57BL/6J background." (PMID 26814757, 2016). "Insulin sensitivity index has repeatedly been documented to be associated with increased cholesterol synthesis in a hyperglycemia-independent manner." (PMID 26728801, 2016). "The first sign of DM is hyperglycemia along with progressive decreases in insulin secretion due to dysfunction of pancreas or loss of response of cells to insulin." (PMID 27721485, 2016). "Fasting hyperglycemia increased in parallel to the loss of insulin secretion from week 9–12 up to approximately 25 mM fasting glucose." (PMID 27153060, 2016). "The correlation between fasting hyperglycemia and cortisol is caused by the glucocorticoid outcomes on hepatic gluconeogenesis and insulin secretion." (PMID 27478508, 2016). "For those adolescents who did have salivary glucose concentrations suggesting hyperglycemia, high salivary glucose concentrations were associated with increased levels of salivary insulin and VEGF-A and reduced salivary levels of IL-12p70." (PMID 27069678, 2016). "Insulin treatment decreased the blood glucose levels to some extent; but failed to ameliorate the oxidative stress, which is a “hallmark” of hyperglycaemia." (PMID 27164129, 2016). "Rapid-acting insulin analogs (when compared to regular human insulin) before meals is associated with a lower incidence of hypoglycemia and minimal postprandial hyperglycemia." (PMID 27148163, 2016). "On diet group, dyslipidemia and hyperglycemia associated to high insulin levels and an increase in the percentage of VAT and hepatic TG deposition were observed at 12 and 24 weeks." (PMID 26921251, 2016). "Gestational diabetes is characterized by hyperglycaemia caused by the inability to compensate for increased insulin demands during pregnancy." (PMID 27070593, 2016).
Hyperglycemia (continued). "Further, insulin therapy is mandatory when hyperglycemia derives from rejection or other causes of graft failure." (PMID 28702248, 2016). "The condition is characterized by chronic hyperglycaemia caused by immune-mediated beta (β) cell elimination or defects in insulin secretion and/or insulin action." (PMID 27070593, 2016). "Glucocorticoids increase hepatic gluconeogenesis, reduce peripheral glucose uptake, inhibit insulin secretion and cause postprandial hyperglycaemia." (PMID 27392119, 2016). "Hyperglycemia is a longer-term risk and is largely due to under-delivery of insulin, which can occur because of poor control, reduced insulin sensitivity, or infusion set faults." (PMID 30740333, 2016). "We found that feeding these animals a diet supplemented with curcumin markedly attenuated the development of hyperglycemia, increased circulating insulin levels, prevented β-cell loss and lengthened the lifespan." (PMID 27110686, 2016). "Hyperglycemia and impaired insulin action and/or insulin secretion are associated with macro- and microvascular complications of high morbidity and mortality." (PMID 27598258, 2016). "Here we report that loss of Drosophila HNF4 recapitulates hallmark symptoms of MODY1, including adult-onset hyperglycemia, glucose intolerance and impaired glucose-stimulated insulin secretion (GSIS)." (PMID 27185732, 2016). "In this disorder, deficiency of insulin action, secretion or both causes impaired metabolism of glucose, which leads to hyperglycemia." (PMID 27054124, 2016). "It is understandable that repeated and prolonged exposure to hyperglycemia leads to β-cell degradation, reduces glucose-stimulated insulin secretion and eventually causes β-cell apoptosis." (PMID 27255377, 2016). "T1D is characterized by profound hyperglycemia due to absolute insulin deficiency caused by immune associated destruction of the insulin-producing beta cells of the pancreas." (PMID 28702252, 2016). "The interaction of hyperglycemia, hyperinsulinemia causes the insulin resistant state and contribute to central adiposity which result in chronic inflammation." (PMID 27405474, 2016). "Our patient developed insulin-deficient hyperglycemia and DKA following 2 months of hyperglycemic symptoms and therefore met the diagnostic criteria for acute-onset T1D." (PMID 27520566, 2016). "Postprandial inflammation and oxidative stress are postulated to be products of hyperglycemia and lipemia and are associated with impaired insulin sensitivity." (PMID 26225995, 2015). "They found that systemic overexpression of leptin ameliorates hyperglycemia in a near-complete insulin-deficient mouse model." (PMID 25870537, 2015). "A recent study analyzed the association of 37 hyperglycemia susceptibility loci with three key traits that influence blood glucose: insulin sensitivity, β-cell insulin processing and insulin secretion." (PMID 25982967, 2015). "Type 2 diabetes (T2D) is a chronic metabolic disease resulting from defects in insulin secretion and insulin action and glucagon suppression, which cause hyperglycaemia." (PMID 25710465, 2015). "CrHis supplementation offer improvements to markers of disease risk, including hyperglycemia insulin sensitivity, and increased oxidative stress." (PMID 25652875, 2015). "Although glucose is the main regulator of insulin biosynthesis and secretion, chronic hyperglycemia is associated with impaired function of insulin secretion." (PMID 25625842, 2015). "Insulin sensitivity in ZDSD animals reflects the progressive hyperglycemia and augmented insulin secretion before beta cell loss as animals age." (PMID 25961053, 2015). "Diabetic mice were treated with insulin to avoid adverse effects of hypoinsulinemia and hyperglycemia, including dehydration, severe weight loss, extensive nephropathy, and neuropathy." (PMID 26106332, 2015). "Alloxan injection lead to glucose intolerance concomitant with fasting hyperglycemia and almost complete loss of insulin response." (PMID 25938469, 2015).
Hyperglycemia (continued). "Impaired insulin responsiveness in fat, muscle, and liver cells leads to failure of glucose absorption despite excessive insulin secretion, resulting in hyperglycemia and associated organ damage in T2D patients." (PMID 26658276, 2015). "Decreased insulin secretion and action are frequently associated with the simultaneous occurrence of hyperglycemia and dyslipidemia." (PMID 26576435, 2015). "This chronic pathology is characterized by hyperglycemia caused by defective insulin action, insulin secretion, or the combination of both." (PMID 26523148, 2015). "These diabetic Apoe−/− mice exhibited the classical features of STZ-induced insulin-deficient type 1 diabetes, such as severe hyperglycemia, hyperphagia, low body weight gain, and low insulin concentration." (PMID 26606676, 2015). "In susceptible individuals, the sustained increase in insulin secretion leads to the failure of pancreatic β-cells and the progression to T2D and marked hyperglycemia." (PMID 25961014, 2015). "Our previous study showed that HFD-induced NAFLD in rats is associated with decreased insulin activation of glycogen synthase and increased gluconeogenesis, which, in turn, exacerbates hyperglycemia." (PMID 25922835, 2015). "Their study used electric acupuncture at bilateral ST36 and SP6 acupoints in 52 female patients and found that acupuncture was associated with prevention of hyperglycemia because of increased insulin sensitivity." (PMID 26230945, 2015). "Severe CCB poisoning is often associated with significant hyperglycemia due to L-type calcium channel in pancreatic β-cells, as well as dysregulation of the insulin-dependent or phosphatidylinositol three-kinase pathway." (PMID 26075111, 2015). "Insulin is used to treat hyperglycaemia in critically ill patients but can cause hypoglycaemia, which is associated with poorer outcomes." (PMID 25613747, 2015). "Two recent studies in European adults suggest that altered branched chain and aromatic AA metabolism is associated with impaired insulin sensitivity prior to the development of hyperglycaemia." (PMID 25693751, 2015). "Null of IRS1 in mice causes not only insulin-resistant and hyperglycaemia, but also significant growth retardation during intrauterine and smaller size than wild-type (WT) littermates postnatal age in 4 months." (PMID 25978640, 2015). "Hyperglycemia is primarily caused by the failure of pancreatic β cells to sufficiently secrete insulin and compensate for the insulin resistance of tissues." (PMID 25574213, 2015). "The attenuated action of insulin on circulating glucose levels causes the pancreas to secrete more insulin to maintain blood glucose homeostasis, leading to hyperglycemia and IR." (PMID 26302954, 2015). "DM is a heterogeneous group of metabolic disorders that occurs either due to resistance of the body to respond to insulin or due to the insufficient production of insulin in the pancreas, both of which cause elevated levels of blood sugar (hyperglycemia)." (PMID 26681965, 2015). "Chronic hyperglycemia also causes oxidative stress in beta cells, leading to impaired glucose-induced insulin secretion and apoptosis of beta cells." (PMID 25938469, 2015). "It is a syndrome characterized by polydipsia, polyuria and hyperglycemia due to either a deficiency in the production or secretion of insulin, diminished tissue response to the actions of insulin, or both." (PMID 26106444, 2015). "Prandial insulin (short-acting insulin administered before meals to limit postprandial hyperglycemia) is associated with a greater frequency of hypoglycemia than long-acting basal insulin." (PMID 26239457, 2015). "Because of the reduction of insulin:glucagon molar ratio, basal endogenous glucose concentration will be higher, causing fasting hyperglycemia and contributing to excessive postprandial glucose rise." (PMID 25961284, 2015).
Hyperglycemia (continued). "Hyperinsulinemia causes tissues to become desensitized to insulin and subsequently insulin resistance develops causing chronic hyperglycemia which can have deleterious effects on the circulatory and renal systems if left untreated." (PMID 26593941, 2015). "As insulin is required for an efficient cellular uptake of glucose to convert it into energy, the ineffectiveness of insulin causes elevated blood glucose levels (hyperglycemia)." (PMID 25786107, 2015). "Fasting plasma glucose was not different between groups at either time point confirming that, similar to humans, loss of insulin sensitivity occurs early in disease progression in rhesus monkeys in advance of hyperglycemia." (PMID 26063458, 2015). "Akita mice have a single amino acid substitution in the insulin 2 gene that causes misfolding of the insulin protein, progressive loss of β-cell function, and significant hyperglycemia as early as 4-5 weeks of age." (PMID 25918731, 2015). "Diabetes type I is characterized by the destruction of insulin producing beta cells in the pancreatic islets, producing insulin deficiency and resultant hyperglycemia." (PMID 26681965, 2015). "It has been established that while glucose crosses the placenta, insulin cannot and therefore maternal hyperglycaemia causes a subsequent fetal hyperglycaemia and hyperinsulinaemia resulting in increased birthweight." (PMID 26555879, 2015). "STZ causes pancreatic beta cell destruction, accompanied by hyperglycemia and a reduction of blood insulin levels." (PMID 26389944, 2015). "Type 1 diabetes (T1D) is caused by autoimmune destruction of the insulin-producing β cells in the pancreatic islets, leading to insulinopenia and hyperglycaemia." (PMID 26646829, 2015). "More specifically, in the liver-specific iNOS transgenic mice, increased Akt S-nitrosylation was associated with impaired insulin signaling and hyperglycemia." (PMID 26172834, 2015). "Cancer cells use more glucose than normal cells, and hyperglycemia elicits hyperinsulinemia and activation of insulin/insulin-like growth factor pathway, which has been linked to aggressive PCa." (PMID 25897669, 2015). "Insulin has traditionally been the drug of choice for managing hyperglycemia in this setting, but carries a significant risk of hypoglycemia." (PMID 28702223, 2015). "By augmenting glucose-dependent insulin secretion and inhibiting glucagon secretion these medications also target the underlying pathophysiology found in patients with stress-induced hyperglycemia." (PMID 28702223, 2015). "In agreement with previous reports, we found that alloxan significantly decreased blood insulin levels and consequently led to hyperglycemia in rats, since it is known to cause pancreatic β-cell damage, resulting in the reduction of insulin production in rats." (PMID 25695047, 2015). "Type-2 DM is characterized by insulin and leptin resistance, contributing to hyperglycemia and dyslipidemia, which are associated with altered sympathetic nervous system (SNS) signaling and CV dysfunction." (PMID 25996498, 2015). "It is characterized by defects in pancreatic insulin secretion or action causing hyperglycemia attributable to disturbances in carbohydrate, fat and lipid metabolism." (PMID 25971249, 2015). "On the etiological basis, factors which contributed to the DM and hyperglycemia are reduced secretion of insulin, inherited or acquired insulin deficiency, ineffectiveness of insulin, and low glucose utilization with high production of glucose." (PMID 26273663, 2015). "This insulin insensitivity and associated hyperglycemia indicated that these animals had developed insulin-resistant diabetes." (PMID 26366723, 2015). "NDM presents as insulin requiring persistent hyperglycemia occurring in the first 6 postnatal months, associated with insufficient production of endogenous insulin." (PMID 26576310, 2015).